TNF (tumor necrosis factor)
Diseases named in the same sentence as TNF in open-access papers (continued):
Sharing a sentence is not in itself a finding about the gene and the disease.
infectious disease (continued). "Indeed, since the majority of human TNF promoter SNPs have been found to be in linkage with HLA molecules, SNPs may also be in linkage with other genes in the MHC locus with functional effects upon resistance and susceptibility to infectious disease." (PMID 17637837, 2007). "While there are no reports on the role of TNF-alpha and/or of the TNFA gene in diseases of camels, in cattle, a closely-related species, TNFA polymorphisms have been associated with multiple infectious diseases and with fertility." (PMID 31590341, 2019). "Conversely, high concentrations of TNF-α as observed in some infectious diseases are not accompanied with widespread endothelial barrier loss." (PMID 27603666, 2016). "Our data show that TNF/CHP nanoparticles effectively enhance both humoral and cellular immunity and could be a potential adjuvant for vaccines against infectious diseases, especially in the mucosa." (PMID 26421290, 2015). "Moreover, in human infectious diseases, GZMK has been found to activate protease-activated receptor-1 (PAR-1) in endothelial and fibroblast cells and induce the production of inflammatory cytokines, such as TNF-α, IL1, IL-6, and MCP-1." (PMID 34603038, 2021). "In this paper, we have demonstrated that chronic SCI patients without associated inflammatory and infectious diseases show functional impairment of circulating monocytes, with diminished TLR4 expression, increased LPS-induced TNF-α production and defective phagocytosis." (PMID 33451043, 2021). "In fact, in infectious diseases dysregulation of numerous ADAM substrates such as junction molecules (e.g., E-cadherin, VE-cadherin, JAM-A), adhesion molecules (e.g., ICAM-1, VCAM-1, L-selectin), and chemokines and cytokines (e.g., CXCL16, TNF-α) has been observed." (PMID 33392273, 2020). "Herbal medicine probably controls the infectious disease mainly based on immunomodulatory agents stimulation (such as GSK3B, MAPK14, PPARγ) will probably help innate and adaptive immune, and regulation the inflammatory cytokines and proinflammatory mediators (like IL-6, IL-8, TNF-α, COX2)." (PMID 29301573, 2018). "In conclusion, we conclude that 7 days of weight loss programs undertaken in preparation for competition might degrade immune functions and conduct to the appearance of infectious diseases such as URTI symptoms in male judo athletes by the increase of proinflammatory cytokines (i.e., IL-6; TNF-α)." (PMID 26075039, 2015). "Our findings that bipolar inhibitory neurons are regulated more strongly by IL-18 and TNF-α and subsequently lead to an overall hypoexcitability of the neural network and may explain symptoms such as dizziness or an increase in NREM sleep during infectious diseases." (PMID 27065940, 2016).
kidney disease (225 papers, 1995 to 2025). "Various studies have indicated that the tumor necrosis factor (TNF) pathway plays a role in the development of different renal diseases, and TNF-related biomarkers are also linked with levels of albuminuria or glomerular filtration rate (GFR)." (PMID 38765394, 2024). "We also observed that the combination of TMAO and TNF-α increased the release of several inflammatory mediators associated with kidney disease." (PMID 38643262, 2024). "Detection of other proteins known to be associated with kidney disease (including complement proteins, proinflammatory extracellular matrix, and cytokines) was also enhanced in TNFα-treated organoid proteome." (PMID 37580326, 2023). "TNFα itself does not cause kidney disease, but programs associated with accelerated kidney disease share similarities with TNFα controlled transcriptional programs, especially on the individual patient level." (PMID 37580326, 2023). "Crucially, however, we extend our study beyond solely a description of the expression of these gene products by also demonstrating the functionality and relevance of gene product networks in our organoid model system to TNFα-associated kidney disease." (PMID 37580326, 2023). "IL-6 and TNF-α have been determined to display high expression in CKD while the abnormal expression of IL-10 is also implicated as a risk factor for kidney disease." (PMID 35496058, 2022). "The pathophysiological mechanisms of kidney diseases are associated with factors that predispose to redox imbalance and the generation of inflammatory mediators, including ROS, TNF-α and IL-1β." (PMID 36077498, 2022). "Epidermal growth factor receptor (EGFR) and tumor necrotic factor-α (TNF-α) play important roles in renal hemodynamics, and they have been reported to be associated with some renal diseases." (PMID 34501555, 2021). "Several studies have reported that TNFα is associated with the development/progression of kidney diseases through the activation of TNF/TNFR pathway." (PMID 33441916, 2021). "Both IL-6 and TNF-α are pleiotropic cytokines that have been implicated in various forms of renal disease." (PMID 33343804, 2020). "TNF‐α genetic polymorphisms were strongly related to renal disorders, haematological manifestation and elevated prevalence of positive anti‐dsDNA antibody in patients with SLE." (PMID 33079487, 2020). "Additionally, TNF-α increases the permeability of the glomerular filtration barrier, causing proteinuria, a common sign of kidney disease." (PMID 39744177, 2025). "The pathogenic role of TNF signaling pathway in kidney disease has been extensively reported." (PMID 38770013, 2024). "TNFα is an inflammatory factor associated with renal disease progression and is known to have two distinct receptors, TNFR1 and TNFR2, with extracellular structural domains capable of being cleaved to form soluble TNFR (sTNFR), which circulates in the bloodstream." (PMID 39211444, 2024). "In fact, TNFα and IL-6 levels were demonstrated to be strongly linked to renal disease progression." (PMID 36986825, 2023). "We demonstrated how we could use our defined system to learn novel pathobiology relevant to TNFα associated kidney disease." (PMID 37580326, 2023). "TNF-α is one of the important factors that cause kidney disease." (PMID 35624699, 2022). "Proinflammatory cytokines and TNF-induced apoptosis are some of the underlying mechanisms that may explain the virus-induced renal diseases that are here reviewed." (PMID 34381495, 2021). "Moreover, studies have determined that tumor necrosis factor alpha (TNFα) is a well-known inflammatory cytokine associated with the progression of kidney disease." (PMID 32183005, 2020). "Also other authors have found that the inflammatory marker TNF-alpha was associated with the severity of DR in type 1 diabetic participant with kidney disease." (PMID 24259948, 2013).
kidney disease (continued). "Patients with kidney diseases often exhibit a microinflammatory state, characterized by elevated levels of interleukin-6 (IL-6), tumor necrosis factor-alpha (TNF-α), and C-reactive protein (CRP)." (PMID 41356816, 2025). "CD68 serves as a marker for macrophages and plays a significant role in the development of numerous renal disorders, especially when pro-inflammatory cytokines such as TNF-α and IL-1β are present." (PMID 40529491, 2025). "On the other hand, extensive research on the inflammatory response in renal disorders has shown that increased pro-inflammatory cytokines such as IL-6 and TNF-α can promote apoptosis." (PMID 39906624, 2025). "The interaction of Nrp1 with TGF-β and TNF-α suggests its potential involvement in acute injury and the chronic progression of kidney disease." (PMID 38977708, 2024). "Although numerous reports highlight the role of TNF-α overexpression in the pathogenesis of renal disease, the mechanisms by which normal TNF-α levels contribute to preserving kidney function have received scant attention." (PMID 39830664, 2024). "Little is known about the effects of anti–tumor necrosis factor (TNF) therapy on kidney disease progression and mortality among patients with new-onset IBD." (PMID 38625700, 2024). "The role of serum and urine TNF and TNFR2 levels as biomarkers is critical due to the availability of several targeted anti-TNF drugs in immunological diseases, which needs further evaluation in renal disease." (PMID 39455940, 2024). "Progressing renal disease exposes individuals to proinflammatory cytokines such as tumor necrosis factor (TNF), interleukin-1 (IL-1), and IL-6, exacerbating bone turnover abnormalities." (PMID 39697967, 2024). "Inflammatory cytokines, such as IL-1 and tumor necrosis factor α (TNF-α) are shown to induce Saas mRNA expression in various diseases including kidney diseases in both patients and experimental animals." (PMID 38791162, 2024). "In summary, in vitro, TNFα-treated kidney organoids create a novel model that faithfully represents the cellular states of the inflammatory response during the progression of renal disease such as nephritis." (PMID 39871891, 2024). "In recent years, several studies have highlighted the role of TNFR2 and TNF-α in kidney disease progression." (PMID 39455940, 2024). "The current existing research has focused mainly on how TMAO or TNF-α alone affects the progress of kidney disease." (PMID 38643262, 2024). "Using transcriptional profiling, we recently demonstrated that proinflammatory molecular signals, likely orchestrated through cytokines such as TNFα, were observed in kidney tissue from individuals with poor clinical outcomes in proteinuric kidney disease." (PMID 37580326, 2023). "Kidney disease represents a state of chronic inflammation arising from an increase in proinflammatory mediators, such as TNF-α, CRP, and interleukin-6." (PMID 37096248, 2023). "Tumor necrosis factor alpha (TNFα) and its receptors, TNFR1 and TNFR2, have been shown to be elevated in renal diseases associated with SARS-CoV-2 infection across diverse patient populations." (PMID 37626956, 2023). "C5α is a potent pro-inflammatory mediator that correlates with the severity of various renal diseases and induces the synthesis of IL-6 and TNF-α in rat GMCs through MAPK signaling pathway activation." (PMID 36791156, 2023). "The proteome of TNFα-treated organoids demonstrated a canonical response reminiscent of that observed in lipopolysaccharide (LPS) triggered kidney disease models." (PMID 37580326, 2023). "Pro-inflammatory cytokines, such as tumor necrosis factor (TNF-), interleukin-1 (IL-1), and interleukin-6 (IL-6), play a primary role in renal disease." (PMID 37305825, 2023). "Ιn healthy kidneys, the levels of TNFα are very low, whereas they increase in many kidney diseases upon leukocyte infiltration, as activated monocytes and macrophages are its primary source." (PMID 35806457, 2022).
kidney disease (continued). "The role of TNF-α in the pathogenesis of kidney diseases depends on the engagement of receptor-specific and/or common signaling cascades." (PMID 35328704, 2022). "Animal studies are the primary source of evidence for the role of TNF-α in the development of kidney diseases." (PMID 35328704, 2022). "One of the potential mechanisms adding to the relationship between DII and the risk of renal disease is the impact of diet-related chronic inflammation in the upregulation of various pro-inflammatory mediators like TGF-β, TNF-α, IL-6, and CRP." (PMID 36313098, 2022). "In vitro and in vivo experimental studies have found that the inflammatory cytokine TNF-α can induce the production of reactive oxygen species (ROS), and further promote oxidative stress and inflammation in the process of renal disease." (PMID 36364876, 2022). "NF-κB, a transcription factor, is closely involved in the regulation of renal disease progression, as it promotes the transcription of pro-inflammatory cytokines, such as TNF-α, IL-6, and ICAM-1." (PMID 35295738, 2021). "AKI stimulates release of pro-inflammatory cytokines (TNFα, IL-6), further exacerbating kidney disease." (PMID 34025658, 2021). "TNF plays a significant role in the progression of renal disorders interacting with the kidney in a paracrine or autocrine manner." (PMID 32046074, 2020). "Several studies demonstrated that systemic TNF-α inhibition attenuates renal function and inflammation in many kidney disease animal models." (PMID 32028746, 2020). "Increased levels of interleukin-6 (IL-6) and tumor necrosis factor-alpha (TNF-α) involved in the inflammatory response predict poor outcome in patients with renal disease." (PMID 33375198, 2020). "Many inflammatory factors play a critical role in renal diseases, such as TGF-β1, TNF-α, and IL-1β; the activation and proliferation of intrinsic cells were resulted by them, and then, the occurrence and progression of renal diseases is aggravated." (PMID 33312224, 2020). "Qualitative RT-PCR analysis revealed that G-Hes treatment downregulated mRNA expressions of Saa3, C/EBPβ, ColI, αSMA, and TNF-α, indicating a possible role of G-Hes in suppressing inflammation and fibrosis in adenine-induced kidney disease." (PMID 31575974, 2019). "Nevertheless, we observed a robust increase in the mRNA expression of TWEAK and TNF-α in the early phase, which was already shown to contribute to the disease pathology in mice, as well as human, kidney disease." (PMID 28927419, 2017). "Tumor necrosis factor-alpha (TNF-α)/NF-κB signaling has been recognized as one of the key pathways in the development of inflammation in many kidney diseases including DKD." (PMID 28713834, 2017). "MCP-1 is the only known inflammatory marker showing increased levels in early HFD-induced kidney disease, which further recruits macrophages that enhance the release of inflammatory mediators, including TNF-α and IL-6." (PMID 26291618, 2015). "Tumor necrosis factor alpha (TNFα), a primary proinflammatory cytokine, is considered to be a potential mediator involved in several kidney diseases, such as renal injury and PKD." (PMID 26110849, 2015). "The pathophysiologic role of TNF-α in mediating kidney disease has been well defined by numerous studies." (PMID 26014479, 2015). "The essential role of TNFα pathway in pathogenesis of various renal diseases including GN has been documented in earlier clinical and experimental models." (PMID 26177311, 2015). "NF-κB plays an important role in the Ang II/AT1 receptor-mediated TNF-α signaling, renal inflammation, and progression of renal disease." (PMID 26245758, 2015). "Studies show high TNF-α levels in patients with advanced kidney disease and proteinuria." (PMID 39941397, 2025). "Metabolic disorders in individuals with kidney diseases may activate the NF-κB signaling pathway, facilitating the release of inflammatory mediators such as IL-6 and TNF-α." (PMID 41356816, 2025).
kidney disease (continued). "Although this association is not yet comprehensible, a tie-up between renal disease and markers of inflammation - interleukin-6 (IL-6), preceded by TNF-α - is eminent." (PMID 38883059, 2024). "However, the co-existence of TMAO and TNF-α (and/or other pro-inflammatory factors) in the renal interstitium is closer to the pathophysiologic background of kidney disease." (PMID 38643262, 2024). "However, a pause in research is evident concerning the TNF-α gene with kidney disease in the inhabitants of India." (PMID 38883059, 2024). "We also found, using the Olink proteomic platform, that TNF-α and TMAO enhanced the secretion of additional inflammatory-and growth mediators associated with kidney disease; VEGFA, GDNF, CDCP1, OPG, uPA, AXIN1, MMP-1, MMP-10, PD-L1, HGF, Flt3L, 4E-BP1, CD40, CASP-8, ADA, TNFRSF9, TWEAK44–61." (PMID 38643262, 2024). "Similarly, only a modest performance of the signature score was observed when the Organoid TNF signature was applied to tissue transcriptomic data from other groups of kidney disease types." (PMID 37580326, 2023). "Additionally, half of these proteins were secreted, raising the potential for identification of additional serum or urine biomarkers of TNFα activity in human kidney disease." (PMID 37580326, 2023). "To investigate whether TNF-Tg mice have a similar pathology to clinical RA patients with concurrent liver and kidney disease, we examined the pathological changes in the livers and kidneys of these mice." (PMID 37784156, 2023). "Some studies report that anti-TNF is safe in RA patients with kidney disease." (PMID 35962246, 2022). "It is worth adding that daily urinary albumin excretion is correlated with levels of TNF-α in urine and with renal expression of TNF-α, which suggests that enalapril may protect patients with kidney disease against albuminuria." (PMID 35163696, 2022). "TNF-α/IL-1β induces Ca2+ influx from the extracellular space and Ca2+ release from intracellular stores, leading to ROS generation and cell damage in several kidney diseases." (PMID 36077498, 2022). "As we know, Ang II and TNF‐α are important mediators in kidney disease." (PMID 33523554, 2021). "TNFα is also elevated in kidney disease and correlates with high creatinine and low eGFR." (PMID 34067023, 2021). "TNF-α, an important regulatory factor, which can promote the production of IL-6, IL-1β, and other cytokines, participates in inflammation, oxidative stress and damage in various renal diseases." (PMID 32765640, 2020). "A large number of studies have reported that serum TNF-α levels significantly increased in the acute phase of renal disease, significantly decreased in the recovery period, was positively correlated with the amount of urine protein, and that TNF-α is involved in the pathogenesis of PNS." (PMID 33817188, 2019). "A stellar example is the use of Adalimumab in the Novel Therapies for Resistant FSGS (FONT) trial based on experimental and clinical data supporting the role of tumor necrosis factor α (TNF-α) in the pathogenesis of a wide spectrum of kidney diseases including FSGS." (PMID 30231499, 2018). "Notably, TNF-α-deficient mice had blunted Ang II-induced hypertensive responses and reduced kidney damage in the model of Ang II-mediated kidney disease, confirming a role for kidney-derived TNF-α to promote Ang II/AT1 receptor-induced renal injury." (PMID 26245758, 2015). "In particular, tumor necrosis factor α (TNFα) has an important role in kidney disease." (PMID 25098821, 2014). "On the other hand, it has been shown that overload of albumin in the proximal tubule promotes tubule interstitial injury leading to progression of renal disease through different pathways, including the accumulation of pro-inflammatory chemokines and cytokines such as TNF-α and IL-6." (PMID 24736406, 2014).